TNF (tumor necrosis factor)
Diseases named in the same sentence as TNF in open-access papers (continued):
Sharing a sentence is not in itself a finding about the gene and the disease.
diabetes (continued). "In addition, the expressions of pro-inflammatory factors (IL-1β and TNF-α) are downregulated by overexpressing miR-20b-3p in the diabetic retina." (PMID 36292956, 2022). "The high-glucose environment of diabetes significantly increases the cytokines, such as interleukin 4(IL-4), interleukin 5(IL-5), interleukin 6(IL-6), interleukin 13(IL-13), and tumor necrosis factorα (TNF-α)." (PMID 35669482, 2022). "The results showed that the GMP intervention group could further reduce the inflammatory reaction induced by diabetes by reducing the levels of IL-6, TNF-α, and CRP and increasing IL-10." (PMID 35399678, 2022). "However, when an inter-group comparison was made between non-diabetes and diabetes, the values of both IL-6 and TNF-α were significantly different among both the NDISCs and NDISPs." (PMID 36557041, 2022). "Both the activated and resting states of neutrophils from patients with diabetes exhibit an extremely increased secretion of tumor necrosis factor (TNF)-α, interleukin (IL)-8, and IL-1β, and elevated levels of inflammatory cytokines are associated with increased susceptibility to pathogens." (PMID 36079032, 2022). "In addition, the blockade of TNF-α prevented the development of diabetes after the transfer of lymphocytes from NOD mice." (PMID 35887317, 2022). "In the Diabetes Prevention Program, the lifestyle intervention was effective in reducing type 2 diabetes incidence in individuals with higher genetic risk, such as risk variants in PPARG and TNF." (PMID 35501401, 2022). "However, the function of TNF-α is pleiotropic; in diabetes, osteoporosis, and rheumatic arthritis, TNF-α inhibits the functions of LOX." (PMID 36146878, 2022). "In the process of atherosclerosis, inflammation is one of the important pathological factors in which C-reactive protein (CRP), TNF-α, IL-6, and other inflammatory cytokines play an important role in the occurrence and development of large vessel atherosclerosis in diabetes." (PMID 36212957, 2022). "Diabetes both up- and down-regulates genes in a TNF-dependent manner." (PMID 36304447, 2022). "Univariate Logistic regression analysis showed that BMI, diabetes, smoking history, systolic blood pressure, diastolic blood pressure, white blood cell, HDL-C, fasting blood glucose, LVEF, serum YKL-40, and serum TNF-α were the risk factor for STEMI (P < 0.05)." (PMID 36051575, 2022). "Diabetes is also associated with upregulation of vascular inflammation including the induction of pro-atherogenic mediators in the thoracic aorta, including the adhesion molecule (VCAM-1) and inflammatory markers (TNFα, IL-6, MCP-1, CD11b, and KLF3)." (PMID 35624851, 2022). "For example, increased circHIPK3 stimulated the activation of the TLR4 pathway and NLRP3 inflammasome and the production of pro-inflammatory cytokines (e.g., TNF-α, IL-1β) in gouty arthritis whereas its silencing alleviated inflammatory damage in myocarditis and diabetes mellitus." (PMID 36072601, 2022). "Neutralizing IFN-γ and TNF-α in vivo in NOD mice prevents development of diabetes." (PMID 35925682, 2022). "It seems likely that ferroptosis in the liver of diabetic animals is accompanied also with the increase in level of the inflammatory cytokines (primarily TNF-α), since Fer-1 treatment abolishes the diabetes-induced increase in the level of this commonly studied marker of inflammation in the liver." (PMID 36012572, 2022). "Protein uptake progressively increased in cells exposed to “diabetes-like” conditions (HG, HG+TNFα lanes) and is independent of T148 mutation." (PMID 35168949, 2022). "Proinflammatory cytokines such as tumor necrosis factor (TNF), IL-1, IL-2, and IL-6 are overexpressed in diabetes and Alzheimer’s disease patients’ brains, indicating the role of inflammation in neuronal damage, likely through the downregulation of the pro-inflammatory microglial function." (PMID 35682821, 2022).
diabetes (continued). "In some previous randomized trials, vitamin D3 supplementation reduced high-sensitivity C-reactive protein (hs-CRP) in patients with diabetes, psychiatric disorders, and polycystic ovary syndrome, and reduced tumor necrosis factor-α (TNF-α) in patients with diabetes." (PMID 36558465, 2022). "Besides, the M1 polarization markers, including IL-1β, IL-6 and TNF-α increased in the isolated retinal microglia from diabetes rats, with the decreasing M2 polarization markers such as IL-4, IL-10 and TGF-β." (PMID 35300330, 2022). "In addition, compared to healthy individuals, plasma TNF-α levels are significantly elevated in both types of diabetes patients." (PMID 36186138, 2022). "To test whether CPI-DM may be preventable by neutralizing IFN-γ and TNF, we treated young NOD mice with anti–IFN-γ and anti–TNF-α and compared the time to diabetes with anti–PD-L1 treatment." (PMID 35925682, 2022). "The core of neuroinflammation is likely the same in aging, metabolic diseases such as hypertension and diabetes, or cerebral insults such as stroke and injury, and inflammatory mediator tumor necrosis factor-α (TNF-α) was proved to serve as a key player and biomarker of neuroinflammation." (PMID 35993019, 2022). "In silico analyses predicted that HOTAIR is involved in various diabetes mellitus-related pathways, including apoptotic cell death, tumor necrosis factor (TNF), ras-mitogen-activated protein kinase (MAPK), forkhead box O (FoxO), and hypoxia-inducible factor 1 (HIF1)." (PMID 35359879, 2022). "During diabetes, the level of the inflammatory factor TNF-α is also elevated." (PMID 36139080, 2022). "TNF-α inhibits tyrosine phosphorylation of insulin receptor substrate-1 aggravating insulin resistance and increases ventricular hypertrophy and vascular permeability leading to heart failure in diabetes." (PMID 36187088, 2022). "The present study confirmed that TNF-α expression was upregulated in patients with diabetes and diabetic combined metabolic syndrome, with more pronounced upregulation in patients with diabetic combined metabolic syndrome, suggesting that the patients were in an inflammatory state." (PMID 35360475, 2022). "The JNK pathway is implicated in diabetes, inflammatory bowel disease, cardiovascular disease, cancer, and others, where the loss of JNK signaling results in the inhibition of tumor necrosis factor (TNF)-stimulated cell death." (PMID 36012674, 2022). "For example, autoimmunity in diabetes may release inflammatory cytokines, such as IL-1β and TNFα, which contribute to a chronic inflammatory state." (PMID 35631084, 2022). "In addition, the oxidative stress produced by diabetes can also produce many inflammatory cytokines, such as TNF-α, IL-6, and transforming growth factor β." (PMID 35669482, 2022). "Insurance claim data from the USA showed that RA patients with a previous history of cardiovascular disease, comorbidity of type 2 diabetes mellitus, or age over 65 years had a lower HR for cardiovascular events when using abatacept than when using TNF inhibitors." (PMID 36430392, 2022). "Finally, the ability of CM to ameliorate the levels of elevated hormones, TNF-α and TGF-β1, produced in response to diabetes, is one of the underlying mechanisms for such a protective effect." (PMID 35334901, 2022). "However, a statistically significant difference (p-value of less than 0.05) in PI, BoP and PD and in the values of IL-6 and TNF-α was found when a comparison was made between the non-diabetes and prediabetes group." (PMID 36557041, 2022). "It was connoted that in patients with diabetes, increased TNF-α and leptin levels might provoke the inflammatory pathways that could contribute to hepatic fibrogenesis." (PMID 35223941, 2022). "Several other comorbidities, such as diabetes, hypertension, dyslipidemia, and smoking, were examined for a possible association with serum TNF-α and CCL2 levels, without any significant results." (PMID 36613708, 2022).
diabetes (continued). "Type 2 diabetes mellitus (T2D) is the result of a dysregulation of insulin production and signalling, leading to an increase in both glucose concentration and pro-inflammatory cytokines such as interleukin (IL)-6 and tumour necrosis factor (TNF)-α." (PMID 36463286, 2022). "Furthermore, interleukin-1β and tumor necrosis factor (TNF)-α are found abundant in a tumor microenvironment in diabetes due to pancreatic cancer, which somehow explains the impaired beta-cell function observed in patients with pancreatic cancer." (PMID 35222270, 2022). "Similarly, studies in type 2 diabetes mellitus in mice have presented a reciprocal regulation between adiponectin and tumor necrosis factor α affecting the regulation of both coronary and aortic endothelial functions." (PMID 36330203, 2022). "The therapy with this drug not only lowered the level of pro-inflammatory markers such as C-reactive protein (CRP) or TNF-α, but also increased levels of anti-inflammatory cytokines which ultimately led to reduce the inflammation in the blood serum of patients with diabetes." (PMID 35468904, 2022). "Report shows that the interaction between TNFα and TNFR causes increase in inflammation via cytokines production that are involved in autoimmune diseases like inflammatory bowel disease, RA, systemic sclerosis and diabetes." (PMID 35289351, 2022). "The crude extract of Centella asiatica was tested against rat kidney and brain oxidative and inflammatory stress caused by diabetes; the authors reported elevated levels of malondialdehyde (MDA), TNF-α, and IFN-γ and reduced antioxidant status in both kidney and brain of diabetes-induced rats." (PMID 35887090, 2022). "However, the odds of having a heart attack in participants with diabetes increased by 20 fold in presence of high levels of triglycerides, TNFα and IL6 if coupled with low levels of HDL-C." (PMID 33510184, 2021). "Metformin could not only improve autophagy and mitochondrial function in diabetes but also decrease inflammation by down-regulate pro-inflammatory cytokines, such as IL-6 and TNF-α." (PMID 33855034, 2021). "Diabetes triggered TNFα response (15%) in untreated diabetic kidney." (PMID 33562428, 2021). "Age, diabetes, IL-6 and MMP-9 were significantly associated with a stiffness of ≥7.2 kPa in the multivariate model that included both demographic factors and serum-based markers (ghrelin, IL-6, TNFα and MMP-9)." (PMID 34813621, 2021). "In a TCR transgenic mouse model of diabetes, T cells responding to islet antigen showed a Tfh phenotype with high IL-21 expression, and the pancreas-infiltrating T cells were shown to express IL-21, IFNγ, and TNFα." (PMID 35156097, 2021). "We investigated the effects of a lemon extract (LE), containing ≥20.0% total flavanones and ≥1.0% total hydroxycinnamic acids, on insulin signaling in murine 3T3-L1 adipocytes treated with TNF-α, which was used to mimic in vitro the insulin resistance condition that characterizes diabetes mellitus." (PMID 34361563, 2021). "The risk of TB infection is high in patients with diabetes, solid organ transplant, renal disease, COPD, hematologic malignancies, diseases under long-term glucocoticoid treatment or tumor necrosis factor treatment, undernutrition, or smoking and alcohol consumption." (PMID 34107991, 2021). "Cluster 2, including 44% (n = 14) of the patients, was characterised by increased levels of vascular inflammatory proteins: fibrinogen, TF activity, PAI-1, and their mediator TNFα, a higher HbA1c, older age, a greater duration of diabetes, and increased BMI, and lower eGDR." (PMID 33730349, 2021). "In the absence of an immunostimulant, diabetes is associated with an increased pro-inflammatory cytokine response marked by increased secretion of IL-1, IL-6, IL-8 and TNF-α, which in turn play a more deleterious role in Covid-19 infection." (PMID 34090396, 2021).
diabetes (continued). "Furthermore, pro-inflammatory cytokines (interleukin -1β, interleukin -6, interleukin -8, tumor necrosis factor-α) were progressively elevated as diabetes and dyslipidemia worsened." (PMID 33828528, 2021). "By pathway analysis, we found these miRNAs to be associated with inflammatory response, chemokine and cytokine mediated signaling and diabetes-related pathways, with a core around TNF, a known modulator of immune response and a key player in immune-mediated diseases, including type 1 diabetes." (PMID 34691048, 2021). "TNF-α can lead to the development of diabetes by affecting insulin action, and levels of inflammatory cytokines and markers are reported to be increased in diabetes patients." (PMID 34867341, 2021). "This could explain the mechanism by which MSCs exert their hypoglycemic and cardioprotective effects by suppressing inflammatory markers, TNF-α and IL-6, that both play a role in the progression of diabetes and atherosclerosis." (PMID 33737713, 2021). "Furthermore, IFN-γ or TNF-α has protective effects in experimental autoimmune encephalomyelitis models or diabetes models when administered late in the disease process." (PMID 32671658, 2021). "Moreover, pharmacological blockade of p300/CBP significantly reduced the diabetes-associated inflammatory response in the kidney, as demonstrated by the knock-down effects on MCP-1, TNFα, NOS2, ICAM-1, VCAM-1, and E-selectin transcript levels." (PMID 34572988, 2021). "Likewise, inflammatory molecules, such as tumor necrosis factor α or hyperglycemic conditions, as present in diabetes, can also change the integrity." (PMID 33478148, 2021). "Interestingly, several studies have attributed changes in vascular permeability, especially those occurring in diabetes, to TNF-α overexpression." (PMID 34829612, 2021). "Furthermore, diabetes is accompanied by an inflammatory state and oxidative stress, which are characterized by elevated levels of C-reactive protein, tumor necrosis factor-alpha, interleukin-6, and reactive oxygen species." (PMID 34876114, 2021). "Many studies have indicated that the tumor necrosis factor alpha (TNF-α) may affect insulin action thus leading to the development of diabetes." (PMID 34067027, 2021). "At baseline, all the markers demonstrated a positive association with the prevalence of CKD, but at the 15-year follow-up, results showed only TNF-α and IL-6 were associated with the prevalence of CKD, which researchers attributed to other comorbidities such as diabetes and hypertension." (PMID 34068841, 2021). "Systemic levels of inflammation mediators, such as CRP, TNF-α, and IL-6, are elevated in periodontal disease and may represent the link between diabetes and periodontitis." (PMID 34833990, 2021). "In one study, including T1D with T2D subjects with periodontitis, it was found that the GCF levels of IL‐1β and TNF‐α were significantly higher in the T1D subjects as compared to the T2D subjects and these levels were negatively affected by the duration of the diabetes." (PMID 33369174, 2021). "Studies have reported that diabetes-induced gliosis eventually leads to the production and release by MGCs of inflammatory molecules such as interleukin-1β (IL-1β), interleukin-6 (IL-6), tumor necrosis factor-α (TNF-α), and chemokine ligand-2 (CCL2)." (PMID 34071438, 2021). "The nodes of the PPI network demonstrated 39 nodes for the pathway of Th17 cell differentiation, 26 nodes for type 1 diabetes mellitus, 30 nodes for Th1 and Th2 cell differentiation, 30 nodes for NF-kappa B signaling pathway, 31 nodes for Apoptosis, and 28 nodes for TNF signaling pathway." (PMID 34697343, 2021). "In the present study, the treatment with peptides delayed development of nephropathy in in vivo model of diabetes, resulting in reduction of albuminuria, urinary TNF‐α and TNFR1 levels, membrane thickness, and mesangial expansion compared to diabetic control mice." (PMID 33634991, 2021).
diabetes (continued). "Thus, more systemic inflammatory circulating markers such as IL-6, TNF-α, and CRP levels significantly increased and were detrimentally respective to the risk and the development of type 2 diabetes mellitus." (PMID 34917685, 2021). "Meanwhile, there was some data manifesting that curcumin could decrease serum TNF-α levels in diabetes rats." (PMID 33602334, 2021). "Similarly, a significant decrease in circulating levels of TNF-α after 12 weeks of osteopathic manual treatment was noted in people with diabetes mellitus and comorbid chronic low back pain." (PMID 34071880, 2021). "Since excessive generation of IL-6 and TNF-α compromise insulin sensitivity, suppression of IL-6 and TNF-α by carnosine and histidine can have beneficial effects on reducing or preventing diabetes-related complications as well as preventing altered endothelial function by inflammation." (PMID 34203479, 2021). "As prolonged inflammation and oxidative stress are linked to unsuccessful wound healing in patients with diabetes, we investigated the effects of PBM on the proinflammatory cytokines IL-6 and TNF-α, as well as the proinflammatory mediator cox-2 in diabetic wounded fibroblast cell culture models." (PMID 33628374, 2021). "In addition, in a rat diabetes model, exposure to Blautia was positively correlated with inflammatory indicators including, IL-1β, TNF-α, IL-6 and lipopolysaccharides." (PMID 34110438, 2021). "These factors include age less than five years, human immunodeficiency virus (HIV) infection, use of immunosuppressive medications such as glucocorticoids and tumor necrosis factor-α (TNF-α) inhibitors, chronic kidney disease, smoking, diabetes mellitus, and undernutrition." (PMID 34270546, 2021). "Moreover, TNFα levels also showed intestinal layer-dependent differences in health and diabetes as confirmed by immunofluorescence, immunogold electron microscopy and ELISA." (PMID 34572059, 2021). "Monocyte hyperactivity may be reversed in patients with diabetes mellitus by scaling and root planing inducing lower monocyte derived TNF-α, high sensitivity CRP, and sE-selectin levels." (PMID 34776994, 2021). "Here, we observed a marked alteration of the major pro- and anti-inflammatory cytokines involved in diabetes pathogenesis, including IL-10, IL-6, and TNF-α in the diabetic rats, which significantly attenuated after treatment by heat-killed Actinomycetales species." (PMID 33880360, 2021). "This study showed that the CRP, IL-6, TNF-α levels in saliva were higher in diabetics than healthy controls, supporting the hypothesis that the pathogenesis of type 2 diabetes mellitus involves subclinical chronic inflammation." (PMID 33676486, 2021). "Moreover, higher concentration of Cys was positively correlated with markers of inflammation including C-reactive protein (CRP) and tumor necrosis factor-α (TNF-α), suggesting higher risk of diabetes complications." (PMID 34335259, 2021). "Actually, they are reported to inhibit the production of key cytokines such as TNF-α (tumor necrosis factor-alpha) and IL-6 (interleukin-6), released in most inflammatory processes and involved in many diseases such as autoimmune ones, diabetes, atherosclerosis, and cancer." (PMID 35011233, 2021). "However, our data demonstrate that TNFα and IL-1b receptor blockade prevents the cardiac electrical remodeling in diabetes." (PMID 34202017, 2021). "Since HspB4/αA-crystallin is induced in MGCs during diabetes, we also studied the effect of HspB4/αA-crystallin overexpression on metabolic stress conditions more reminiscent of diabetes, that is high glucose and TNFα." (PMID 34071438, 2021). "In addition, after adjusting for age, sex, smoking, BMI and diabetes duration, the levels of LDL-C, HbA1c, UACR, IL-6, and TNF-α are independent risk factors for painful DPN." (PMID 33777989, 2021). "Moreover, 6-gingerol ameliorates renal fibrosis and pathological changes via the decrease in expression of TNF-α protein in streptozotocin-induced diabetes." (PMID 33670981, 2021).